NPHP4 (nephrocystin 4)
Description:
Involved in the organization of apical junctions; the function is proposed to implicate a NPHP1-4-8 module. Does not seem to be strictly required for ciliogenesis. Required for building functional cilia. Involved in the organization of the subapical actin network in multiciliated epithelial cells. Seems to recruit INT to basal bodies of motile cilia which subsequently interacts with actin-modifying proteins such as DAAM1 (By similarity). In cooperation with INVS may down-regulate the canonical Wnt pathway and promote the Wnt-PCP pathway by regulating expression and subcellular location of disheveled proteins. Stabilizes protein levels of JADE1 and promotes its translocation to the nucleus leading to cooperative inhibition of canonical Wnt signaling. Acts as a negative regulator of the hippo pathway by association with LATS1 and modifying LATS1-dependent phosphorylation and localization of WWTR1/TAZ.
Synonyms: KIAA0673; SLSN4; POC10
Tractability: PROTAC: ubiquitination databases record sites on it.
Gene: Protein-coding gene on chromosome 1 (5,862,804 to 5,993,455, reverse strand). Ensembl gene ENSG00000131697.
Subcellular location: Cytoplasm, cytoskeleton, cilium basal body; Cytoplasm, cytoskeleton, microtubule organizing center, centrosome; Cell junction, tight junction; Nucleus
Subcellular location (Human Protein Atlas): Nucleoplasm; Cytosol; Nuclear bodies; Vesicles
Pathways (Reactome):
Organelle biogenesis and maintenance: Anchoring of the basal body to the plasma membrane
Signal Transduction: Signaling by Hippo
Gene Ontology:
Molecular function: protein binding; structural molecule activity
Biological process: negative regulation of canonical Wnt signaling pathway; positive regulation of bicellular tight junction assembly; actin cytoskeleton organization; cell-cell adhesion; protein localization to ciliary transition zone; signal transduction; visual behavior
Cellular component: cell-cell junction; centrosome; nucleus; ciliary basal body; ciliary base; ciliary transition zone; cytosol; non-motile cilium; NPHP complex; bicellular tight junction; centriole; cytoplasm; cytoskeleton; photoreceptor connecting cilium; photoreceptor distal connecting cilium; ribbon synapse
Genetic constraint (gnomAD): Loss-of-function variants: 143 observed, 138.86 expected, observed/expected ratio (o/e) 1.03, 90% interval 0.9 to 1.18. The upper end of that interval is the gene's LOEUF score, 1.18, which puts it in group 5 of 6, group 1 being the genes least tolerant of losing a copy. Missense variants: 1,878 observed, 1,839.8 expected, observed/expected ratio (o/e) 1.02, 90% interval 0.98 to 1.06. Synonymous variants: 813 observed, 785.31 expected, observed/expected ratio (o/e) 1.04, 90% interval 0.98 to 1.1.
Gene-disease validity (ClinGen):
ClinGen rates the evidence that NPHP4 causes each of these diseases.
nephronophthisis 4 (autosomal recessive): Definitive. Any nephronophthisis in which the cause of the disease is a mutation in the NPHP4 gene.
Homologues: Orthologues: chimpanzee NPHP4 (99% identical), macaque NPHP4 (93% identical), dog NPHP4 (79% identical), pig NPHP4 (78% identical), mouse Nphp4 (78% identical), rat Nphp4 (78% identical), guinea pig NPHP4 (66% identical), tropical clawed frog nphp4.2 (56% identical), Caenorhabditis elegans nphp-4 (22% identical), zebrafish nphp4 (5% identical).